IL1A (interleukin 1 alpha)
Diseases named in the same sentence as IL1A in open-access papers (continued):
Sharing a sentence is not in itself a finding about the gene and the disease.
atherosclerosis (continued). "Thus, diacerein may reverse IL-1α’s effects on atherosclerosis and also reduce its expression by ECs via suppressing IL-1β activity." (PMID 28323859, 2017). "Additionally, both IL1β and IL1α contribute to the pathogenesis of experimental atherosclerosis." (PMID 21698167, 2011). "The IL-1 family of cytokines, especially IL-1β and IL-1α, plays a critical role in the pathogenesis of various inflammatory disorders, including inflammatory bowel disease (IBD), atherosclerosis, ischemia/reperfusion injury, coronary artery disease, and PTB." (PMID 41227337, 2025). "Various local or systemic cytokines are increased in obesity, including IL-1α, TNF-α, leptin, and IL-6, while IL-1α, in combination with TNF-α and IL-6, is involved in the pathology of atherosclerosis in obese individuals." (PMID 36311488, 2022). "Previous studies have confirmed that atherosclerosis is mainly attributed to inflammation and the products of pyroptosis such as IL-1β, IL-18, IL-1α, ATP, and GSDMD-N, suggesting crucial role of pyroptosis in the pathogenesis of atherosclerosis." (PMID 36304814, 2022). "The severity of atherosclerosis correlates with inflammasome activity and NLRP3/caspase 1-mediated generation of IL-1β and IL-1α in human atherosclerotic plaque." (PMID 33172487, 2020). "Disturbed balance in the action of IL1A, IL1B and IL1RA leads to the development and progression of atherosclerosis." (PMID 31480765, 2019). "Inflammatory cytokines, including tumor necrosis factor alpha (TNF-α), interleukin (IL) 1α (IL1α), IL1ß, IL-2, IL6 and IL8 are involved in the pathogenesis of atherosclerosis, participating in all stages of this condition." (PMID 30479572, 2018). "Therefore, the action of IL-1α may suffice to allow cell migration and compensatory remodeling when targeting IL-1β to reduce inflammation in atherosclerosis, avoiding the potentially adverse effects of abrogation of signaling by both isoforms noted in IL-1R1-deficient mice." (PMID 27032103, 2016). "On the other hand, while searching for a set of genes associated with the MAPK signaling pathway, we found a group of four DEG members of this pathway: PLA2G4A, IL1A, RASGRP3, and DDIT3, which are molecules related to inflammation, apoptosis, signal transduction, and atherosclerosis." (PMID 40332370, 2025). "A study has reported that fatty-acid-mediated mitochondrial uncoupling facilitates NLRP3-independent interleukin 1α (IL-1α) release in vitro, but not that of IL-1β, and atherosclerosis development in vivo." (PMID 33807807, 2021). "Measurement of cytokines and proteases in the supernatants of HAoSMCs confirmed that inflammatory mediators, such as CXCL8, IL-6, IL-1β, and IL-1α and proteases, such as MMP-10 [role in atherosclerosis and vascular calcification], were produced and released by HAoSMCs upon aging in vitro." (PMID 34313809, 2021). "Neutralization of IL-1α and IL-1β by induction of neutralizing antibodies resulted in reduced atherosclerosis in Nrf2+/+ApoE−/− but not in Nrf2−/−ApoE−/− mice." (PMID 32596261, 2020). "Overall, IL-1α is a potential target for the treatment of atherosclerosis, although the target is not perfect." (PMID 33362770, 2020). "This leads to the release of an array of pro-inflammatory cytokines, such as interleukin-1-alpha (IL-1α), IL-1β, IL-6, tumor necrosis factor-alpha (TNF-α) and matrix metalloproteinases (MMPs), which further exacerbates atherosclerosis by promoting immune cell infiltration." (PMID 31357404, 2019). "Unexpectedly, the fatty acids elicit release of IL-1α but not IL-1β, revealing a selective IL-1α-persistent pathway of vascular inflammation and pathology, and suggesting a role of IL-1α in atherosclerosis." (PMID 29329335, 2018). "However IL-1α’s effect was still pro-atherogenic because TNFAIP3 is reported to decrease inflammation and atherosclerosis in murine models." (PMID 28323859, 2017).
atherosclerosis (continued). "This study investigated whether IL-1α and IL-1β overlap in regulating the expression of MMP-3 and other remodeling-related proteases in isolated human cells relevant to atherosclerosis in primary culture and in fresh human carotid endarterectomy specimens." (PMID 27032103, 2016). "Inflammatory modulators/biomarkers, such as IL-1α, IL-1β, IL-6, IL-12, IL-15, IL-18, and tumor necrosis factor α, or alternative anti-inflammatory cytokine IL-10, and adhesion molecules (ICAM-1, VCAM-1), involved in atherosclerosis progression have been shown to predict cardiovascular diseases." (PMID 37374202, 2023). "As active IL-1α can be produced in the absence of the NLRP3 inflammasome through calpain-mediated processing, deficiency of the NLRP3 inflammasome would not impair the development of atherosclerosis." (PMID 31354731, 2019). "We show that senescent VSMCs establish an inflammatory SASP driven by IL-1α that may have multiple negative effects on atherosclerosis." (PMID 26139463, 2015). "We therefore applied a nongenetic gain-of-function PCSK9-AAV8 atherosclerosis model to address the question whether atherosclerosis development depends on IL-1α or the NLRP3 inflammasome and whether IL-1α expressed at the cell surface is involved in the development of atherosclerosis." (PMID 37701434, 2023). "Indeed, we show that IL-1α potently drives VSMC proliferation via NF-κB.Interestingly, the well-reported reduction in plaque size upon thrombin inhibition wasabsent in IL-1αTM/Apoe−/− mice, suggesting the action ofthrombin inhibitors on atherosclerosis are, in part, via reduced IL-1α activation." (PMID 37309666, 2023). "Indeed, if a significant aspect of inflammation in atherosclerosis is driven by IL-1α, the effects in CANTOS may not seem as efficacious as required, or at worse the trial may fail losing a real therapeutic opportunity." (PMID 26139463, 2015). "Here, a non-genetic model was applied to characterize the role of IL-1α, IL-1β, and NLRP3 for the pathogenesis of atherosclerosis." (PMID 37701434, 2023). "The production of IL-1α is not reliant on NLRP3 activation, so lack of its key components would not affect atherosclerosis." (PMID 36082127, 2022). "However, in the initial stages of atherosclerosis, IL-1α may be absent." (PMID 36555579, 2022). "Since IL-1α does not need NLRP3 activation to be generated, missing its key components would not affect atherosclerosis." (PMID 32648087, 2021). "One study showed that the absence IL-1α significantly decreased atherosclerotic plaque area in a high-fat diet C57BL/6 mouse model, and the absence of IL-1β did not reduce atherosclerosis development in a statistically significant manner." (PMID 31354731, 2019).
breast cancer (83 papers, 2006 to 2025). A primary or metastatic malignant neoplasm involving the breast. "Weak evidence was noted for the association of genetically predicted IL-1α level with all breast cancer (OR 1.01, 95% CI 0.99–1.03, P = 0.2167)." (PMID 38263420, 2024). "For example, in the MMT-Her2 model of breast carcinoma, IL-1α deficiency delayed tumor development, probably by reduction of inflammatory microenvironment, and by reduction of cancer stem cells (CSCs) in primary tumors." (PMID 38612760, 2024). "Tumor cell-derived IL-1α has been linked with higher metastasis in lung cancer and breast cancer, indicating potential therapeutic value for blocking the IL-1α/IL1R/MyD88/TET2 axis." (PMID 35140725, 2022). "IL-1, a prototypic pro-inflammatory cytokine that presents itself in two forms, i.e., IL-1α and IL-Iβ, seems to be involved in different molecular mechanisms underlying primary breast cancer development and the formation of metastasis in bone." (PMID 31847214, 2019). "IL-1B has been linked with poor prognosis in breast cancer, whereas tumour-induced IL-1A has been linked to CCL22 production by tumour-infiltrating immune cells." (PMID 29760166, 2018). "In one study comprising Tunisian patients with breast cancer the IL1A TT (homozygous mutant) genotype was associated with impaired prognosis in patients with breast cancer." (PMID 19267917, 2009). "Thus, the effects produced by IL-1α deficiency in 4T1 breast cancer cells in culture are a complex combination of both potentially pro- and anti-tumorigenic phenomena." (PMID 38612760, 2024). "Another study also showed that high expression of IL-1α in breast cancer biopsies was associated with tumor dedifferentiation and more malignant phenotypic behavior, hence supporting the previous study of IL-1α’s role in tumorigenesis and potential CSC generation and maintenance." (PMID 33430381, 2021). "Moreover, we have previously shown that JNK signaling, that induces IL-1α/β in breast cancer cells, is linked to basal-like breast cancer." (PMID 32198421, 2020). "Moreover, stimulation of multiple cancer cell lines, including MCF-7 breast cancer, A375 melanoma, prostate stem cells and murine primary mammary cells, with IL-1α inhibited cell proliferation by causing G0–G1 cell cycle arrest." (PMID 31231372, 2019). "Polymorphisms in Il1a are associated with increased breast cancer risk." (PMID 23484019, 2013). "In the present study, the IL1RN long/2 gene polymorphism was independently associated with an unfavourable prognosis in breast cancer patients, while presence of the mutant alleles of IL1A -889 and IL1B +3953 were only associated with a shortened overall survival in a univariate analysis." (PMID 19267917, 2009). "We acquired data regarding C-reactive protein (CRP), interleukin (IL)-1a, IL-1b, and IL-6 expression and BC related to single nucleotide polymorphisms (SNPs) from two larger consortia (the genome-wide association studies and the Breast Cancer Association Consortium)." (PMID 38263420, 2024). "The authors concluded that a breast-myeloid cell axis, mediated via TSLP and IL-1α, promotes the progression of breast cancer and metastasis formation." (PMID 40873585, 2025). "Activation of primary breast cancer tissues, as well as surrounding tissue, released several proinflammatory cytokines (i.e., IL-1α, IL-1β, IL-18, and IL-33)." (PMID 40873585, 2025). "The effects of intracellular IL-1α on the development of triple negative breast cancer (TNBC) in mice were assessed using the CRISPR/Cas9 system to suppress IL-1α expression in 4T1 breast cancer cells." (PMID 38612760, 2024). "This is in accord with our findings, showing uncontrolled growth of IL-1α KO breast cancer cells in immunocompromised mice but limited growth in WT mice." (PMID 38612760, 2024). "In this study, we examined the influence of interleukin 1α (IL-1α) on the development of an immunosuppressive TME using orthotopic transplantation murine models of breast cancer." (PMID 38746389, 2024).
breast cancer (continued). "IL-1α knock-out in breast cancer cells led to diminished tumor infiltration by myeloid-derived suppressor cells (MDSC), and to increased recruitment of antigen-presenting and cytotoxic cells into the tumor site." (PMID 38612760, 2024). "Here, we demonstrate, for the first time, that intracellular IL-1α in breast cancer cells can alter the TME to ensure their survival via expression of pro-inflammatory molecules and recruitment of myeloid immunosuppressive cells." (PMID 38612760, 2024). "This body of evidence indicates the necessity for a more careful evaluation of the biology of IL-1α in TNBC development in order to design novel therapeutic approaches for this severe form of breast cancer that is resistant to conventional treatment." (PMID 38612760, 2024). "Our results demonstrate that IL-1α gene knockout induces substantial changes in the transcriptome of 4T1 breast cancer cells." (PMID 38612760, 2024). "In breast cancer, other cytokines such as IL‐6, IL‐1α, IL‐1β, IL‐8, TNF‐α/β, TGF‐β, and GM‐CSF are also known to stimulate angiogenesis." (PMID 36815234, 2023). "Our findings show that Spalax senescent secretome abrogated SASP and inhibit breast cancer cell migration by targeting IL-1α." (PMID 36982207, 2023). "Studies have shown that IL-1α inhibits cell proliferation of MCF-7 breast cancer, A375 melanoma, prostate stem cells, and murine primary mammary cells by causing G0–G1 cell cycle arrest." (PMID 37445686, 2023). "IL1A, as a proinflammatory cytokine, was upregulated in many types of cancers, such as breast cancer and lung cancer." (PMID 35432539, 2022). "HER2 increased drug-resistance-related CSCs in HER2+ breast cancer patients, yet the blocking of IL-1α signaling improved chemotherapy efficacy when combined with cisplatin and paclitaxel." (PMID 35735628, 2022). "In previous reports, ILs such as IL-18, IL-33, and IL-1α were found to have pro-tumorigenic effects in pancreatic cancer, breast cancer, and leukemia." (PMID 35954317, 2022). "We and others found that acute IL-1α or IL-1β exposure represses ERα and PR mRNA and protein accumulation in breast cancer cell lines." (PMID 35626710, 2022). "It has previously been shown by others that high expression of IL-1A and IL-6 both correlate with poor prognosis for breast cancer patients." (PMID 35260569, 2022). "Higher levels of IL1 β, IL1Ra, IL18, and IL1α in breast cancer tissues and significantly higher IL1 β levels in stage II, III or IV breast cancers were reported." (PMID 35686268, 2022). "In the lung metastasis of breast cancer, IL-1α and IL-1β secreted by breast cancer cells induce the production of CXCL9 and CXCL10 in lung fibroblasts through NF-κB signal transduction, thus promoting the growth of lung metastasis." (PMID 33722297, 2021). "In a study with MCF-7 breast cancer cells overexpressing mature IL-1α, when transplanted into nude mice, the MCF-7 cells swiftly formed fast growing estrogen-dependent tumors." (PMID 33430381, 2021). "A similar function for IL-1A and IL-1B has also been reported: IL-1A and IL-1B produced by breast cancer cells can display the same function by equally activating IL1R1 in lung fibroblasts, which support metastatic colonisation." (PMID 34290237, 2021). "Breast cancer patients with a high expression of IL1A showed poorer RFS (p = 0.042) and DMFS (p = 0.037) than the patients with low expression." (PMID 34203721, 2021). "In a transgenic model of luminal breast cancer, IL-1A is tumour-suppressive and correlates with better prognosis in patients." (PMID 34290237, 2021). "Analogously, via paracrine IL-1α/β signaling, disseminated breast cancer cells reeducate lung fibroblasts and induce their transdifferentiation into CAFs to generate a metastatic niche for breast cancer." (PMID 33407730, 2021).
breast cancer (continued). "Metastatic breast cancer cells educate fibroblasts in lung metastases by secreting interleukin-1 alpha (IL-1α) and interleukin-1 beta (IL-1β), which trigger nuclear factor‐κB (NF-κB) signaling in MAFs." (PMID 34112258, 2021). "Because of the pro-tumorigenic effects of IL-1α, it would be expected that IL-1α would be upregulated in breast cancer cells following hydrolysis products treatment." (PMID 34404457, 2021). "We find that breast cancer cells that have invaded the lungs secrete interleukin 1 alpha/beta (IL-1α/β) to induce the chemokines CXCL9/10 in MAFs." (PMID 32198421, 2020). "CXCR3+ breast cancer cells express high levels of IL-1α/β via JNK signaling, suggesting that they can both induce CXCL9/10 in MAFs and benefit from these chemokines." (PMID 32198421, 2020). "Pathogenic polymorphisms of other inflammatory genes like NRF2, IL1α, IL1β, IL6, IL8, and CXCR2 have also been identified in Tunisian and Egyptian breast cancer patients." (PMID 33659210, 2020). "CXCR3+ breast cancer cells secrete IL-1α/β to stimulate a crosstalk with lung fibroblasts from which they benefit through their CXCR3 receptor." (PMID 32198421, 2020). "In PyMT/ Il1a-/- and PyMT/Il1r1-/- mice, IL-1R1 signaling suppresses mammary tumor cell proliferation early in tumorigenesis and facilitates breast cancer outgrowth with pulmonary metastasis." (PMID 33031059, 2020). "Specifically, IL-1α and IL-1β secreted by breast cancer cells induce CXCL9 and CXCL10 production in lung fibroblasts via NF-κB signaling, fueling the growth of lung metastases." (PMID 32198421, 2020). "Breast cancer aggressiveness can be mediated by IL-1α and IL-8 by increasing metastasis and cachexia." (PMID 31963587, 2020). "In breast cancer, leptin upregulates all components of the IL-1 system (IL-1α, IL-1β, IL-1Ra and IL-1R tI) and both leptin and IL-1 together promote angiogenesis through expression of VEGF/VEGFR." (PMID 33339340, 2020). "More specifically, IL-6 and IL-1α cytokines are known to enhance the promotion of tumor growth, angiogenesis, and metastasis of aggressive human cancers such as breast cancer." (PMID 32526880, 2020). "In line with this, we observed a significant correlation between CXCL9/10 and IL1A/B expression in dissected metastases samples from breast cancer patients." (PMID 32198421, 2020). "Others reported breast cancer cell-derived IL-1α up-regulated IL-22 production of T cells in an AhR- and RORγt-dependent manner, which indicated a direct crosstalk between cancer cells and immune cells." (PMID 32649314, 2020). "These experiments confirm that IL-1α/β are indeed the factors contained within CM from metastatic breast cancer cells that drive CXCL10 expression in lung fibroblasts via IL-1R." (PMID 32198421, 2020). "Our findings suggest a model in which JNK activity in metastasis-initiating breast cancer cells induces expression of IL-1α/β, which interact with IL-1R on lung fibroblasts to stimulate NF-κB-mediated induction of Cxcl9/10." (PMID 32198421, 2020). "Expression of IL-1α, IL-1β, and their receptors in human breast cancer tissues results in the activation of a population of cells and subsequently contributes to angiogenesis, tumor proliferation, and tumor invasion in the microenvironment." (PMID 31182982, 2019). "It does so, in part, by regulating production of GM-CSF, IL1α, IL-6, and TNFα by breast cancer cells." (PMID 29593211, 2018). "Breast cancer represents one of the better-studied models and expresses all the members of the IL-1 system, including IL-1α and β, antagonist IL-1Ra, and receptor IL-1R." (PMID 30154786, 2018). "From the gene coexpression network of BRCA, we see some breast cancer associated genes are isolated, such as ‘TNF’, ‘CD55’, ‘IL1A’." (PMID 29671401, 2018). "IL1A expression was found to correlate with poor differentiation and decreasing ERα expression in breast cancer." (PMID 26618099, 2015).